GPX4 (glutathione peroxidase 4)
Diseases named in the same sentence as GPX4 in open-access papers (continued):
Sharing a sentence is not in itself a finding about the gene and the disease.
myelodysplastic syndrome (5 papers, 2020 to 2025). A clonal hematopoietic disorder characterized by dysplasia and ineffective hematopoiesis in one or more of the hematopoietic cell lines. "In addition, iron overload is often associated with myelodysplastic syndrome (MDS), and iron overload can destroy the bone marrow microenvironment in MDS patients, resulting in decreased bone marrow mononuclear cell viability, decreased GSH and GPX4 activities, and increased ROS." (PMID 38816377, 2024).
oral cancer (5 papers, 2024 to 2025). "Molecular docking confirmed that TFP is a GPX4 inhibitor, and elevated GPX4 expression in oral cancer biopsies was associated with poor prognosis, suggesting that targeting ferroptosis can effectively suppress OSCC progression and represent a novel strategy for cancer therapy." (PMID 40722814, 2025). "For instance, cisplatin-resistant oral cancer cells show increased dependency on GPX4, and their survival is significantly compromised upon GPX4 inhibition." (PMID 40650229, 2025). "Molecular docking studies confirmed direct GPX4 inhibition, and high GPX4 expression in oral cancer biopsies correlated with poor prognosis, highlighting TFP as a promising repositioned drug candidate." (PMID 41227330, 2025). "Trifluoperazine, a repurposed antipsychotic drug, has also been shown to downregulate GPX4 and trigger ferroptosis through reactive oxygen species (ROS) accumulation and autophagy activation in oral cancer cells." (PMID 40650229, 2025). "Researchers have demonstrated that PARL treatment leads to significant lipid peroxidation, glutathione depletion, and GPX4 inactivation in oral cancer cells, confirming that ferroptosis is the primary mechanism." (PMID 40722814, 2025). "Meanwhile, the present study provides evidence that the expression levels of GPX4 in oral cancer biopsy samples were inversely correlated with patient prognosis." (PMID 39664583, 2024). "The elevated expression level of GPX4 in oral cancer biopsies was also found to correlate with a poor prognosis." (PMID 39664583, 2024). "Based on these results, we propose that TFP induces ferroptosis in oral cancer cells by targeting GPX4." (PMID 39664583, 2024). "Glutathione peroxidase 4 (GPX4) is a ferroptosis regulator whose overexpression promotes the proliferation of oral cancer cells." (PMID 38478802, 2024). "Together, these results provide evidence that TFP selectively induces GPX4-mediated, autophagy-dependent ferroptosis, thereby exerting anti-cancer effects against oral cancer and preventable death." (PMID 39664583, 2024). "Treatment with TFP significantly upregulated the expression levels of pro-ferroptotic proteins, such as FTH1 and NCOA4, while downregulating the expression levels of proteins that reverse ferroptosis, such as SLC7A11, GPX4 and Nrf2, in oral cancer cells." (PMID 39664583, 2024). "In conclusion, this study provides evidence that TFP induces ferroptosis in oral cancer cells through a multifaceted mechanism that includes ROS elevation, autophagy, the inhibition of SLC7A11/GPX4 signaling and mitochondrial damage in order to achieve ferroptosis in oral cancer cells." (PMID 39664583, 2024). "Therefore, the anticancer activity of TFP to selectively target GPX4 highlights its therapeutic potential in the treatment of oral cancer." (PMID 39664583, 2024). "Our findings indicate that TFP significantly elevates the levels of lipid-derived reactive oxygen species (ROS) and induces ferroptotic cell death in oral cancer cells through pathways involving autophagy, the SLC7A11/GPX4 axis, and mitochondrial damage." (PMID 39664583, 2024).
sarcoma (5 papers, 2021 to 2026). A usually aggressive malignant neoplasm of the soft tissue or bone. "The SLC7A11 protein was expressed at a high level in HDF, 293T cells, and U2OS sarcoma cells while the expression of GPX4 protein was high in HDF, Aska and Yamato cell lines." (PMID 37444594, 2023). "Based on the results presented above, we propose that sarcoma is characterized by increased expression of TFRC and SHARPIN, with high GPX4 dependency, suggesting that ferroptosis may be a promising therapeutic target for sarcoma." (PMID 37444594, 2023). "RNA pull-down, RNA immunoprecipitation (RIP), and actinomycin D mRNA decay assays were conducted to elucidate the molecular interactions between lncRNA-PRLB, the RNA-binding protein fused in sarcoma (FUS), and glutathione peroxidase 4 (GPX4) mRNA." (PMID 41783067, 2026). "Glutathione peroxidase 4 (GPX4) protects cells against ferroptosis, and its inhibition using RAS-selective lethal 3 (RSL3) had an antitumor effect that was more pronounced in sarcoma cell lines, particularly synovial sarcoma cells, compared to non-sarcoma cells." (PMID 37444594, 2023).
sarcopenia (5 papers, 2021 to 2025). Progressive decline in muscle mass due to aging which results in decreased functional capacity of muscles. "In addition, we discuss the protective role of antioxidant factors such as GPX4 (glutathione peroxidase 4) and antioxidant peptides like SS peptides in mitigating lipid peroxidation and delaying the progression of sarcopenia." (PMID 39963429, 2025). "Our analysis revealed significant differences in the mRNA and protein levels of GPX4 and ACSL4 in sarcopenia patients compared to controls." (PMID 40309008, 2025). "Additionally, GPX4 enhances the activity of muscle/ER Ca2+-ATPase (SERCA), maintaining calcium homeostasis and excitation-contraction coupling, thereby alleviating sarcopenia progression." (PMID 39963429, 2025).
schizophrenia (5 papers, 2018 to 2026). A major psychotic disorder characterized by abnormalities in the perception or expression of reality. "We assessed intracellular Fe2+ content, MDA levels, GSH, and GPX4 in the prefrontal cortex and peripheral blood mononuclear cells (PBMCs) of patients with schizophrenia." (PMID 40021790, 2025). "ERVW-1 transcripts significantly elevated in schizophrenia plasma (n=44) vs. controls (n=37) (p<0.05) by qRT-PCR, negatively correlated with reduced GPX4 and SLC3A2 (p<0.05), supporting ferroptosis role." (PMID 41200560, 2025).
vitiligo (5 papers, 2022 to 2025). Generalized well circumscribed patches of leukoderma that are generally distributed over symmetric body locations and is due to autoimmune destruction of melanocytes. "Targeting ferroptosis in vitiligo treatment is an emerging strategy that focuses on the modulation of GPX4 levels to reduce melanocyte susceptibility to ferroptosis." (PMID 39430757, 2024). "Excessive iron promotes the Fenton reaction, generating more ROS, further damaging melanocytes, while glutathione peroxidase 4 (GPX4), a key regulatory factor in ferroptosis, shows significantly downregulated expression in vitiligo." (PMID 41169396, 2025). "Studies have demonstrated that the expression of GPX4 was significantly downregulated in vitiligo and that exogenous supplementation of GPX4 or iron chelators can alleviate melanocyte damage." (PMID 41169396, 2025). "In clinical research, individuals with vitiligo have exhibited lower levels of arachidonic acid and reduced expression of the antioxidant enzyme GPX4 in their serum compared to healthy counterparts." (PMID 39430757, 2024). "In the analysis of epidermal tissues, it was shown that ferroptosis markers were aberrantly expressed in vitiligo patients, with glutathione peroxidase 4 (GPX4) and ferritin being downregulated at both protein and mRNA levels." (PMID 36439174, 2022). "In conclusion, understanding the role of ferroptosis in vitiligo and targeting key regulators such as GPX4 and SLC3A2 may lead to the development of novel treatments that could improve outcomes for patients with vitiligo." (PMID 39430757, 2024). "Interestingly, IFN-γ exposure did not significantly reduce the expression of GPX4, SLC7A11, or SLC3A2, implying that other factors are involved in the increasing ferroptosis-sensitive state of melanocytes in patients with vitiligo." (PMID 35962439, 2022).
acute liver failure (4 papers, 2022 to 2026). Rapid deterioration of liver function causing encephalopathy and coagulopathy. "In APAP-induced acute liver failure patients (GSE74000), IKBKG levels decreased, and Nrf2 target genes were also repressed (i.e., HMOX1, PRDX1, TXNRD1, GPX4, GPX1, GCLC, GCLM, and NQO1)." (PMID 38505605, 2024). "We then assessed the levels of the biomarker of ferroptosis including GPX4, FTH1, and HMGB1 using a public GEO dataset (GSE74000) obtained from patients with APAP-induced acute liver failure." (PMID 35198058, 2022).
acute lung injury (4 papers, 2021 to 2026). A condition of lung damage that is characterized by bilateral pulmonary infiltrates (pulmonary edema) rich in neutrophils, and in the absence of clinical heart failure. "The in vivo results showed that oral IMP activated the AHR/ALDH3A1 and Nrf2/HO-1/GPX4 pathways in lung tissue, thus improving lung dysfunction and inflammation in acute lung injury (ALI) mice induced by LPS." (PMID 41513604, 2026).
acute pancreatitis (4 papers, 2022 to 2025). An acute inflammatory process that leads to necrosis of the pancreatic parenchyma. "Oxidative stress and glutathione depletion are involved in the onset of acute pancreatitis, and pancreatic-specific Gpx4 deficiency exacerbates cerulein-induced pancreatitis in mice via a trypsin-dependent mechanism." (PMID 37450339, 2023). "For instance, wedelolactone has been shown to activate the anti-ferroptotic enzyme GPX4, thereby protecting against acute pancreatitis." (PMID 41470786, 2025). "Glutathione peroxidase 4 (GPX4)-dependent ferroptosis in pancreatic acinar cells plays a critical role in acute pancreatitis (AP)." (PMID 36670963, 2022). "Further investigations found that inhibiting AP-1 did not reduce GPX4 deficiencies-induced ferroptosis and mitigated acute pancreatitis." (PMID 36670963, 2022). "In the in vitro experiments, we discovered for the first time that ferroptosis occurs in pancreatic duct cells during acute pancreatitis, and that MGST1 is significantly upregulated in duct cells, where it plays a crucial role in negatively regulating ferroptosis via the ACSL4/GPX4 axis." (PMID 40076525, 2025).
allergic asthma (4 papers, 2014 to 2025). A asthma with a basis in a pathological type I hypersensitivity reaction. "The current investigation utilized a mouse model of allergic asthma to assess the impact of BG-NPs on IgE production, lung-infiltrating inflammatory cells, oxidative stress markers, DNA damage, airway remodeling, and GPx4 expression." (PMID 39305381, 2025). "The genes associated with mucin production (GAL3ST2), leukotriene synthesis (GPX4), Th2-mediated allergic asthma (PTBP1, ZFPM1, SBNO2, and EGFL7), and IgE mediated allergy (PAK2) were also represented in our polygenic prediction models of ICS response." (PMID 38540988, 2024). "On the contrary, the hierarchical cluster analysis of the MDR data in women showed that the CYBA 640A>G, GPX4 C718T, and PON2 S311C gene polymorphisms have a strong synergistic interaction effect on the risk of allergic asthma." (PMID 24895604, 2014). "In house dust mite‐induced allergic asthma, increased production of ROS, depletion of glutathione (GSH), and downregulation of glutathione peroxidase 4 (GPX4) and solute carrier family 7 member 11 (SLC7A11) suggest the occurrence of ferroptosis during this process." (PMID 40667723, 2025).
B-cell lymphoma (4 papers, 2021 to 2026). "DLBCL is a type of B-cell lymphoma, and GPX4 also inhibits B-cells' immune infiltration." (PMID 38333875, 2024). "When Gpx4 was deficient, there was increased lipid peroxidation and impaired antibody responses in B1 and marginal zone B cells, which may explain why GPX4-positive patients had poor overall survival than GPX4-negative patients in B-cell lymphoma." (PMID 38259464, 2023). "Immunohistochemical findings showed that Cyt increased 8-hydroxydeoxyguanosine (8-OHdG) and B-cell lymphoma/leukemia-2-associated X protein (Bax) expression, whereas it downregulated Glutathione peroxidase 4 (GPX4) and B-cell lymphoma/leukemia-2 (Bcl-2)." (PMID 41726560, 2026). "Similar to the B cell lymphoma cell lines, HDL NP treatment potently reduced GPX4 expression at both the RNA and protein levels." (PMID 33208460, 2021). "As anticipated, overexpression of GPX4 led to higher GPX4 levels following HDL NP treatment compared with controls and protected B cell lymphoma cells from HDL NP–induced cell death compared with controls." (PMID 33208460, 2021).
brain injury (4 papers, 2023 to 2025). Acute and chronic (see also brain INJURIES, CHRONIC) injuries to the brain, including the cerebral hemispheres, CEREBELLUM, and brain STEM. "Another study reported that 4 weeks of aerobic exercise reversed ferroptosis markers in a traumatic brain injury model, including upregulating the expression of GPx4, Xc−, and FPN1." (PMID 39315073, 2024). "In a mouse model of traumatic brain injury (TBI), the levels of malondialdehyde (MDA), glutathione (GSH), and glutathione peroxidase 4 (GPX4) in brain tissue were detected by enzyme-linked immunosorbent assay (ELISA)." (PMID 37375352, 2023). "Likewise, traumatic brain injury-induced IL-23 upregulation enhanced neuronal ferroptosis through STAT3 activation, while IL-23 neutralization attenuated ferroptosis, restored GPX4 and ACSL4 expression, and normalized STAT3 overactivation." (PMID 41304754, 2025).
cataract (4 papers, 2023 to 2025). Partial or complete opacity of the crystalline lens of one or both eyes that decreases visual acuity and eventually results in blindness. "Notably, we observed that advancing age was associated with a significant increase in FTH1 expression in the LECs of cataract patients, while GPX4 expression showed a corresponding decrease." (PMID 39796164, 2025). "In addition, downregulation of Notch signaling promotes ferroptosis in LEC by impairing the Nrf2/GPX4 antioxidant pathway, which contributes to the development of cataracts." (PMID 40697914, 2025).
experimental autoimmune encephalomyelitis (4 papers, 2022 to 2025). An autoimmune demyelinating disease of the central nervous system that is produced experimentally in animals by the injection of homogenized brain or spinal cord in Freund's adjuvant. "Indeed, deficient GPX4 expression in neurons can cause ferroptotic damage in experimental autoimmune encephalomyelitis models and cause significant neurological sequela." (PMID 35725567, 2022). "In experimental autoimmune encephalomyelitis (EAE) model, a reduction in neuronal GPX4 was also observed." (PMID 40485847, 2025).
gastric tumor (4 papers, 2023 to 2025). "Our results confirmed that the expression of GPX4, CASP6, IL-6, CASP5, CASP4, and TIRAP was greatly up-regulated in gastric tumors relative to normal tissues." (PMID 37595258, 2023). "The expression of GPX4, NRF2, and SLC7A11 in GC was higher than that in normal tissues and varied in different stages of gastric tumor." (PMID 37768308, 2023). "Notably, both GPX4 and FTH1 have been shown to be significantly upregulated in clinical specimens from 30 human gastric tumor cases." (PMID 40610429, 2025).
gestational diabetes (4 papers, 2021 to 2025). Carbohydrate intolerance first diagnosed during pregnancy. "Accordingly, lower GPx4 levels were reported in Chinese patients with gestational diabetes than in control pregnant women, with GPx4 negatively correlated with the fasting 2 h plasma-glucose level and glycated albumin in the second trimester." (PMID 35740085, 2022). "Ferroptosis and gestational diabetes mellitus (GDM) converge at multiple molecular intersections, notably through the involvement of key regulatory genes including GPX4, SLC7A11, ACSL4, and LPCAT3." (PMID 41020807, 2025). "In gestational diabetes, upregulated SIRT3 enhanced autophagy activation by promoting the AMPK-mTOR pathway and decreasing GPX4 levels to induce ferroptosis in trophoblastic cells." (PMID 34869322, 2021). "High glucose increases reactive oxygen species (ROS), malondialdehyde (MDA), and iron content, while decreasing glutathione (GSH) and glutathione peroxidase 4 (GPX4) in HTR-8/SV neo cells; this indicates the involvement of ferroptosis in the gestational diabetes." (PMID 40871742, 2025).
glaucoma (4 papers, 2015 to 2025). Increased pressure in the eyeball due to obstruction of the outflow of aqueous humor. "Western blot analysis showed that the expression of Slc7a11 and GPX4 in the retinas of the glaucoma patients was downregulated compared with the healthy control subjects." (PMID 37371903, 2023). "In glaucoma, iron overload may similarly induce ferroptosis in activated retinal microglia—characterized by GPX4 downregulation and lipid peroxidation—which amplifies neuroinflammatory responses and accelerates RGC loss and optic nerve degeneration." (PMID 41363911, 2025). "GPX4 was expressed in a low level in both normal and glaucoma retinas, but FSP1 was significantly elevated in the RGCL of human glaucoma retinas." (PMID 35637215, 2022).
hyperlipidemia (4 papers, 2023 to 2025). "Specifically, ox‐LDL triggers ferroptosis by suppressing glutathione peroxidase 4 (GPX4) activity, while ferroptosis inhibitors can mitigate this process, ameliorating hyperlipidemia and slowing AS progression." (PMID 40697701, 2025).